HRURF (HR upstream open reading frame)
Description:
May function as an inhibitory translational control element that can negatively regulate protein translation of HR gene.
Synonyms: U2HR; HMU; MUHH
Tractability: No criterion of Open Targets' tractability assessment is met for any kind of drug.
Gene: Protein-coding gene on chromosome 8 (22,130,458 to 22,131,010, reverse strand). Ensembl gene ENSG00000288677.
Diseases named in the same sentence as HRURF in open-access papers:
HRURF is named in the same sentence as 1 disease in open-access papers, as found by Europe PMC text mining. Sharing a sentence is not in itself a finding about the gene and the disease.
HRURF shares sentences with these, for which no sentence is quoted: hypotrichosis (1 paper).